AEBP1 (AE binding protein 1)
Diseases named in the same sentence as AEBP1 in open-access papers (continued):
Sharing a sentence is not in itself a finding about the gene and the disease.
glioma (continued). "Then, we explore the significant correlation between AEBP1 upregulation and increased EGFR expression in primary glioma, and employ a glioma cell line LN229 to identify relevant proteins and molecular pathways through protein network analysis." (PMID 32938364, 2020). "Results show significant correlation between AEBP1 upregulation and increased EGFR expression in primary glioma." (PMID 32938364, 2020). "In our earlier report, we showed that AEBP1 down regulation results in cell death in both U87MG and U138MG glioma cells." (PMID 31601918, 2019). "To verify that previous identified prognostic genes of TCGA-glioma PTEN-mut are also the prognostic genes in IDH1-wt patients with PTEN-mut, we observed that AEBP1, CLCF1, and OS9 were significantly prognostic genes in IDH1-wt, IDH1-wt/GBM, or IDH-wt/LGG gliomas with PTEN-mut." (PMID 34336645, 2021). "Therefore, (+)-JQ1 potentially competes for and binds to the CLCF1, AEBP1, and OS9 proteins, resulting in the interruption of the pro-oncogenic pathway in PTNE-mut gliomas." (PMID 34336645, 2021). "Thus, in the PTEN-mut glioma, CLCF1, AEBP1, and OS9, which are significantly associated with survival time, may induce glioma progression and are critical targets for diagnosis, prognosis prediction, and treatment, giving therapeutic recommendations to glioma with mutant PTEN." (PMID 34336645, 2021). "Knockdown of AEBP1 inhibits GSC proliferation and glioma sphere formation." (PMID 33391492, 2021). "(+)-JQ1 compound may combine and inhibit the CLCF1, AEBP1, and OS9 interacting proteins, and hence, it can be a potential treatment option for PTEN-mut gliomas." (PMID 34336645, 2021). "Data from the Cancer Genome Atlas (TCGA) revealed high expression of AEBP1 in human gliomas, GBM and low-grade glioma (LGG), compared to noncancerous cells." (PMID 32565808, 2020). "AEBP1 was shown to maintain the survival and proliferation of U138MG glioma cells." (PMID 32565808, 2020). "We have observed that MIF is expressed in the four selected glioma cells and in this background, we hypothesized that MIF’s nuclease activity and AIF-mediated recruitment are required for AEBP1 down regulation induced parthanatos." (PMID 31601918, 2019). "On probing the initiator caspases, both caspase 8 (extrinsic or ligand mediated pathway) and caspase 9 (intrinsic or mitochondrial pathway), we observed that neither of these caspases were activated upon AEBP1 down regulation in U138MG glioma cells." (PMID 31601918, 2019). "All these results clearly suggest that classical caspase pathway components are indeed present in U138MG glioma cells, but however, the pathway is not activated under AEBP1 depleted conditions." (PMID 31601918, 2019). "We were curious to examine whether the process of cell death observed in PTEN deficient glioma cells (U138MG and U87MG) also occurs in PTEN proficient glioma cells (LN18 and LN229) upon AEBP1 down regulation." (PMID 31601918, 2019). "Therefore, this study further investigates the consequences of the upregulation of AEBP1 in GBM and its clinical significance, by exploring the effects of AEBP1 expression on glioma proliferation, migration, invasion in vitro, and tumor growth in vivo as well as the underlying mechanisms." (PMID 33224311, 2020).
melanoma (15 papers, 2017 to 2025). A malignant, usually aggressive tumor composed of atypical, neoplastic melanocytes. "AEBP1 was previously implicated in resistance to BRAFi in melanoma, however, its expression is driven by hyperactivation of the PI3K/AKT pathway." (PMID 30143629, 2018). "In melanoma patients, AEBP1 expression was reported in cancer-associated fibroblasts (CAFs)." (PMID 32565808, 2020). "AEBP1 is related to numerous human malignancies, including gastric cancer, colon cancer, glioblastoma, and melanoma." (PMID 37143134, 2023). "Similar experiments suggested that PI3K-Akt pathway further influences AEBP1 expression in PLX4032-resistant melanoma cells." (PMID 32565808, 2020). "Although the exact role of AEBP1 in CAFs in melanoma patients requires further analysis, Hu and colleagues conducted a detailed experiment to examine the potential role of AEBP1 in acquired drug resistance to BRAF inhibition of melanoma via NF-κB pathway." (PMID 32565808, 2020). "AEBP1 possesses the ability to promote tumor progression in PLX-4032-resistant melanoma via NF-κB pathway." (PMID 32565808, 2020). "In melanoma cells, upregulation of AEBP1 confers resistance to BRAF inhibition." (PMID 37686580, 2023). "Additionally, previous studies have reported that AEBP1 activates the NF-κB signaling pathway and promotes tumor progression and drug resistance in colon adenocarcinoma, gastric cancer, and melanoma." (PMID 33224311, 2020). "In BRAF inhibitor-resistant melanoma cells, upregulation of AEBP1 mediated by hyperactivation of the PI3K/Akt-CREB (cAMP response element-binding protein) pathway activated NF-κB activity by accelerating IκBα degradation, thereby conferring acquired resistance to BRAF (V600E) inhibition." (PMID 30097586, 2018). "Consequently, targeting AEBP1 may prove to be an effective therapy for drug resistance in melanoma patients subjected to BRAF inhibitors." (PMID 32565808, 2020). "Phospho-CREB is restored in relapsing melanomas previously treated by MAPK inhibitors, possibly by the up-regulation of adipocyte enhancer-binding protein 1, AEBP1." (PMID 35158973, 2022). "Melanoma-A consisted of CD63, PMEL, and S1000A1, while Melanoma-B consisted of S100B, FTH1, and AEBP1 expression." (PMID 33535416, 2021). "Upon generation of PLX4032-resistant melanoma cells (Mel-CVR18 and Mel-CVR21), cDNA microarray and RT-qPCR analysis of these cells revealed a significant upregulation of AEBP1, compared to Mel-CV cells." (PMID 32565808, 2020). "In this section, we will discuss the relationship of AEBP1 and PI3K-Akt pathway in melanoma, breast cancer, glioblastoma, and leukemia." (PMID 32565808, 2020). "We identified dozens of melanoma-increased genes uniquely down-regulated by ZDL, including C-type lectin domain containing 11A (CLEC11A), intermediate filament family orphan 1 (IFFO1), and AE binding protein 1 (AEBP1)." (PMID 40141086, 2025). "In melanoma and CRC, high expression of AEBP1 in CAFs is positively correlated with both fibroblast biomarker expression and EMT meta scores, suggesting that AEBP1 is responsible for EMT and that AEBP1-mediated EMT may promote fibroblast activity." (PMID 37143134, 2023). "Furthermore, a higher expression of adipocyte enhancer-binding protein 1 (AEBP1) has been shown to confer resistance to BRAF inhibition in vivo, and greater CREB activation is required for AEBP1 overexpression in resistant melanoma cells." (PMID 35805104, 2022). "According to previous studies, upregulated AEBP1 could be regulated by the transcription factor CREB and the PI3K/Akt pathway in melanoma cells, and activation of the PI3K/Akt signaling cascade could be found in diabetic patient-derived peripheral blood mononuclear cells (PBMCs)." (PMID 34332599, 2021). "However, NF-κB pathway is not the only pathway that is influenced by AEBP1 overexpression in melanoma patients with resistance to BRAF inhibition." (PMID 32565808, 2020).
melanoma (continued). "Thus, inhibiting the mediator, AEBP1, may prove to be an effective and practical therapeutic method in combating PLX4032-resistant melanoma." (PMID 32565808, 2020).
Ehlers-Danlos syndrome (13 papers, 2019 to 2025). The Ehlers–Danlos syndromes (EDS) are a clinically and genetically heterogeneous group of heritable connective tissue disorders (HCTDs) characterized by joint hypermobility, skin hyperextensibility, and tissue fragility. "Several independent groups have identified bi-allelic mutations in AEBP1 as the genetic cause of a variant of Ehlers-Danlos syndrome, a systemic connective tissue disorder characterized by defective collagen assembly and impaired ECM integrity." (PMID 41373631, 2025). "Ehlers-Danlos syndrome, Classic-Like, 2 (clEDS2) is a rare genetic disorder caused by biallelic mutations in the AEBP1 gene, which encodes aortic carboxypeptidase-like protein (ACLP)." (PMID 41231548, 2025). "Blueprint Genetics Ehlers-Danlos Syndrome Panel (41 genes) identified three variants in our patient: two identical homozygous variants in AEBP1 c.2923del and a heterozygous variant in COL11A1 c.1160A>G." (PMID 38674395, 2024). "Interestingly, mutations on the AEBP1-encoding gene were implicated with the onset of Ehlers-Danlos syndrome (EDS)." (PMID 38256421, 2024). "In addition, mutations in the AEBP1 gene that encodes ACLP result in Ehlers Danlos Syndrome with vascular complications." (PMID 33597582, 2021). "More recently, AEBP1 was identified as a candidate gene in Ehlers-Danlos syndrome." (PMID 34916661, 2022). "In 2018, a new clinical subtype, caused by biallelic variants in the AEBP1 gene, encoding the ACLP protein, was added to the current nosological classification of the Ehlers-Danlos Syndromes (EDS)." (PMID 36553625, 2022). "Although an early targeted search for AEBP1 mutations in infants affected by gastroschisis did not clearly support a connection, a large number of recent publications have shown that mutations in the AEBP1 gene result in a subtype of autosomal recessive Ehlers-Danlos syndrome (EDS)." (PMID 39050735, 2024).
glioblastoma (12 papers, 2016 to 2025). The most malignant astrocytic tumor (WHO grade IV). "Elevated AEBP1 expression has been linked to proliferation, migration, and invasion in glioblastomas." (PMID 41009755, 2025). "Aebp1 is upregulated in the majority of the primary glioblastoma multiforme (GBM) and loss of Aebp1 function was shown to result in apoptosis." (PMID 27092172, 2016). "For instance, the expression of AEBP1 is frequently upregulated in primary glioblastoma, and silencing of AEBP1 induces apoptosis in glioblastoma cell lines." (PMID 37686580, 2023). "For instance, AEBP1 silencing inhibits cell proliferation and increases apoptotic in primary glioblastomas." (PMID 36352396, 2022). "Our study was aimed at investigating the mechanistic consequences of the upregulation of adipocyte enhancer-binding protein 1 (AEBP1) in glioblastoma (GBM)." (PMID 33224311, 2020). "Studies have shown that AEBP1 is highly expressed in a variety of malignant tumors (such as breast cancer, glioblastoma, bladder cancer, gastric cancer, colorectal cancer, ovarian cancer, and skin cancer)." (PMID 33224311, 2020). "It is worthy of note that this study experimentally demonstrates the therapeutic advantage of targeting AEBP1 in glioblastoma, rendering the inhibition of AEBP1 as a promising therapeutic approach." (PMID 32565808, 2020). "Furthermore, AEBP1 is a potential oncogene, and its overexpression is related to the development and progression of tumors, such as stomach cancer, colorectal cancer, glioblastoma, and bladder cancer." (PMID 36352396, 2022). "For example, AEBP1 is highly expressed and promotes cell proliferation in primary glioblastomas." (PMID 36352396, 2022). "Knockdown of AEBP1 reduces proliferation in various cell lines including colorectal, gastric and glioblastoma cell lines (HT-29, MGC803, XN0422, U87MG, U138MG), and high expression of AEBP1 has been linked with poor prognosis in colorectal and other malignancies." (PMID 36038791, 2022). "In this review, we analyze the effects of AEBP1 overexpression in a variety of malignancies (e.g., breast cancer, glioblastoma, bladder cancer, gastric cancer, colorectal cancer, ovarian cancer, and skin cancer), with a specific focus on the AEBP1-mediated control over the canonical NF-κB pathway." (PMID 32565808, 2020). "In both TCGA and CGGA dataset, the results showed that the expression level of AEBP1 was increased in glioblastoma (GBM) samples, IDH wild-type samples, and MGMT promoter unmethylated samples." (PMID 34373835, 2021). "AEBP1 was upregulated more than 4-fold in most primary glioblastoma multiforme (GBM) cases compared with secondary GBM39." (PMID 30097586, 2018). "While AEBP1 has not been previously shown to regulate the complement system, a study in glioblastoma tissues also found that high AEBP1 expression levels were associated with enrichment for complement and coagulation cascade pathway-related genes." (PMID 39930483, 2025).
Obesity (11 papers, 2010 to 2025). Accumulation of substantial excess body fat. "Subsequent work implicated AEBP1 in obesity and inflammation through a variety of protein-protein interactions." (PMID 39050735, 2024). "Transcriptional repression of aP2 by AEBP1 is physiologically significant since targeted over-expression of AEBP1 in adipose tissue causes diet-induced obesity in mice." (PMID 20396415, 2010). "Adipocyte enhancer-binding protein 1 (AEBP1) rises in obesity, causing a drop in PTEN activity and consequent stimulation of adipocyte proliferation in mice and this increase in adipocyte proliferation may lead to further crosstalk between adipocytes and tumour cells, for instance by leptin." (PMID 36038791, 2022). "AEBP1-null mice are resistant to diet-induced obesity, indicating that AEBP1 plays a key role in regulating body fat." (PMID 41155166, 2025). "The opposite, massive obesity, was observed in female transgenic mice, with AEBP1 overexpression in adipose tissue and macrophages." (PMID 39050735, 2024). "Second, obesity-related factors that have also been linked to NAFLD, including glucose, fructose, and palmitate, increase AEBP1 expression, thereby exacerbating expression of these genes." (PMID 31299062, 2019). "AEBP1 seems to induce massive obesity in mice with targeted, tissue-specific overexpression of AEBP1 (AEBP1TG mice) by inducing adipocyte proliferation in vivo, leading to adipocyte hyperplasia in white adipose tissue." (PMID 20396415, 2010). "However, overexpression of AEBP1 in mice on a high-fat diet resulted in increased obesity." (PMID 40759793, 2025). "Co-immunoprecipitation experiments supported an interaction via the carboxypeptidase domain of AEBP1; this interaction stimulated PTEN degradation and correlated with enhanced adipose apoptosis and resistance to diet-induced obesity in AEBP1 knockout mice." (PMID 39050735, 2024). "AEBP1 falls within an across-breed iHS and a xpEHH signature in Oldenburger on ECA 4 and is reportedly involved in diet-induced obesity and energy homeostasis in mice, where it was upregulated in adipose tissue." (PMID 31022261, 2019). "CNTNAP2, GLI2, DPT (dermatopontin), AEBP1, ITIH5, CXCL11, GDNF (glial cell derived neurotrophic factor), MCHR1, FLT3, ELANE (elastase, neutrophil expressed), OSMR (oncostatin M receptor) and IL15RA are involved in development of obesity, but these genes might be key for progression of HF." (PMID 34218797, 2021).
breast carcinoma (10 papers, 2015 to 2025). "AEBP1 is a transcriptional repressor factor associated with the pathogenesis of various cancers, including thyroid cancers and breast cancers." (PMID 40375334, 2025). "Interestingly, AEBP1 plays a role in the molecular pathway of bone osteoblastic module, a module that has been implicated in the progression of several tumors including breast cancer." (PMID 32565808, 2020). "To determine the cellular source of AEBP1 expression, we analyzed scRNA-seq data from breast cancer tissues (GSE228499)." (PMID 41373631, 2025). "Collectively, these results indicate that in breast cancer tissue, AEBP1 is highly expressed in CAFs and that AEBP1-positive CAFs co-express collagen genes." (PMID 41373631, 2025). "Collectively, these studies highlight AEBP1 as a potential therapeutic target for the inhibition of metastatic breast cancer." (PMID 32565808, 2020). "A gene set enrichment analysis (GSEA) reported that AEBP1 was a highly enriched myoepithelium-type gene in malignant breast tumors." (PMID 32565808, 2020). "In the context of breast cancer tumorigenesis, Aebp1 has been suggested to be involved in the regulation of the cross-talk between mammary epithelium and stroma." (PMID 27092172, 2016). "Previous research has consistently reported that AEBP1 is highly expressed in various solid tumors, including gastric cancer, colorectal cancer, breast cancer, oral cancer and papillary thyroid cancer, where it promotes tumor progression, epithelial–mesenchymal transition and therapeutic resistance." (PMID 41373631, 2025). "Thus, AEBP1 overexpression may be a prominent factor in tumor progression of malignant breast cancer cells through bone differentiation and matrix remodeling." (PMID 32565808, 2020). "The IHC score results demonstrated that ADAMTS12, AEBP1, CXCL11, and EPPK1 protein levels were higher in breast cancer samples than in normal controls." (PMID 35505821, 2022). "Target genes of GLI1 are induced, leading to contribute the cellular properties, such as the proliferation (by AEBP1) and metastasis (by CXCR4) of breast cancer cells." (PMID 26744317, 2016). "In breast cancer (TCGA-BRCA), AEBP1–correlated genes were significantly enriched in categories related to collagen organization and ECM remodeling, across the biological process (GO-BP), cellular component (GO-CC) and molecular function (GO-MF) domains (FDR < 0.05)." (PMID 41373631, 2025).